MSRA (methionine sulfoxide reductase A)
Diseases named in the same sentence as MSRA in open-access papers (continued):
Sharing a sentence is not in itself a finding about the gene and the disease.
kidney cancer (1 paper, 2023). Primary or metastatic malignant neoplasm involving the kidney. "In addition, GCLM is closely associated with the development of kidney cancer, and the ability of MsrA is to protect the kidney against ischemia-reperfusion injury." (PMID 37496661, 2023).
psoriasis (1 paper, 2023). An autoimmune condition characterized by red, well-delineated plaques with silvery scales that are usually on the extensor surfaces and scalp. "We also identified five novel psoriasis risk genes, methionine sulfoxide reductase A, elongation factor for RNA polymerase II (ELL), Myotubularin Related Protein 9 (MTMR9), leucine-rich repeat containing 25 (LRRC25), and single-stranded-DNA-binding protein 4 (SSBP4), among 26 genes." (PMID 37511476, 2023).
selenium deficiency (1 paper, 2009). A nutritional deficiency disease resulting from inadequate selenium levels in the body, which can lead to impaired function of selenoproteins essential for antioxidant defense and thyroid hormone metabolism. "It is possible that the elevation of G6PD in these tissues (subjected to selenium deficiency) serves as a compensation mechanism for the lower antioxidant defense system in the MsrA-/- mice, under conditions of prolonged SD diet." (PMID 19633607, 2009). "Accordingly, it is suggested that the MsrA-/- brain is more vulnerable to selenium deficiency mediated by SD diet due to its relative lower basal selenium content." (PMID 19633607, 2009). "Based on these observations, it was concluded that a lack of MsrA exacerbates the effects caused by prolonged selenium deficiency." (PMID 19633607, 2009).
vitiligo (1 paper, 2019). Generalized well circumscribed patches of leukoderma that are generally distributed over symmetric body locations and is due to autoimmune destruction of melanocytes. "Reduced MsrA and MsrB correlate with senile hair graying, epidermal damage, and vitiligo." (PMID 31282614, 2019).
cancer (10 papers, 2007 to 2025). A tumor composed of atypical neoplastic, often pleomorphic cells that invade other tissues. "The MsrA expression appeared to be different in several human cancer cell lines and MsrA gene promoter analysis showed a cell-specific transcriptional regulation of this gene." (PMID 17519015, 2007). "Recently, we reported that human MsrA gene expression appeared to be different in several human cancer cell lines and gene promoter analysis showed a cell-specific MsrA transcriptional regulation." (PMID 17519015, 2007). "The role of MsrA in regulating Jab1 function in cancer is yet to be determined." (PMID 32456285, 2020). "Since sulindac is a substrate for MsrA, it seemed reasonable that the killing of cancer cells by sulindac might involve oxidative stress." (PMID 19503837, 2009). "Of note, HAAO, MGLL, and UPGE were down-regulated in 18 cancer types; ADHFE1, CAT, and MSRA were down-regulated in 19; and RGN was down-regulated in 21 different types of cancer." (PMID 31351478, 2019). "We retrieve the majority of known cancer genes but also new candidates such as STK31 and MSRA with very high confidence." (PMID 27321817, 2016).
infection (9 papers, 2011 to 2021). The state of being infected such as from the introduction of a foreign agent such as serum, vaccine, antigenic substance or organism. "For example, an infection caused by a NAS that harbors the msrA gene is likely to be unresponsive to erythromycin, assuming that in vivo results mimic those in vitro." (PMID 29503642, 2018). "Genes msrA/B (pilB) were expanded (three copies) in five strains and their gene products can promote the successful infection of humans and also respond to adverse conditions." (PMID 33602135, 2021). "At 24 h after infection with MsrA, B1 or B2 adenovirus vectors, RT-PCR revealed markedly enhanced mRNA contents of MsrA, B1, B2 in transfected cells than in controls." (PMID 30717164, 2019). "Western blot confirmed that 24 h after infection, MsrA, B1, B2 protein contents were also significantly elevated than in control pancreatic stellate cells transfected with only GFP-containing vectors." (PMID 30717164, 2019). "When we focused on antibiotic resistance genes, significant differences were identified in strains from different sources of infection for the mecA, msrA, aadD, aphA3, and sat genes." (PMID 30319561, 2018). "In fact, we found that Drosophila msrA transcription was increased 5-fold in a ΔgcvT mutant infection." (PMID 28586382, 2017). "Taken together, these results show that MetO supplementation or msrA inactivation in enterocytes limits intestinal lipid droplet size leading to survival of infection." (PMID 28586382, 2017). "We tested the susceptibility of the msrAMI14018 and msrAEY05753 mutant fly lines to infection with wild-type V. cholerae after confirming decreased transcription of msrA in these lines." (PMID 28586382, 2017). "It is interesting to note that the msrA mutant strain of M. genitalium is deficient in inducing the proinflammatory cytokine TNF-α, the principal mediator of inflammatory response to infection." (PMID 22558404, 2012). "However, infection with a ΔgcvT mutant results in competitive inhibition of MsrA and increased protein oxidation." (PMID 28586382, 2017). "Hence, this study demonstrates that all three methionine sulfoxide reductases, MsrA, MsrB and MsrC, facilitate growth of a canonical intracellular pathogen during infection." (PMID 22073230, 2011). "In considering the role(s) of MsrA/B/C in microbial pathogenesis, it is important to note that these proteins may become essential under certain growth conditions or during specific stages of infection." (PMID 23437085, 2013).
tumor (8 papers, 2015 to 2025). "We also provided evidence that deletion may decrease mRNA expression of PINX1 and MSRA, which are the other two tumor suppressor candidates located on del8p23.1." (PMID 40699642, 2025). "One example, MSRA, has been found to be a tumor suppressor in other functional studies." (PMID 38721669, 2024). "Moreover, the promoter activities of GCLC, GSR, PRDX1, and MSRA were significantly elevated in HFD tumor cells compared to LFD cells." (PMID 35182054, 2022). "IHC staining of ccRCC TMA revealed that GCLM and MsrA were significantly decreased in tumor tissues, whereas SBNO2 showed no significantly different." (PMID 37496661, 2023).
ischaemic heart disease (1 paper, 2012). "Another gene involved in RA susceptibility, the methionine sulfoxide reductase A (MSRA) gene, in particular the minor allele G, is associated with an increased risk of ischaemic heart disease in anticyclic citrullinated peptide antibodies (ACPAs) positive RA." (PMID 23024462, 2012).
kidney diseases (1 paper, 2023). "Based on the known functions of the DKD candidate marker genes, it appears that many associate with kidney diseases, and our stress score genes, particularly GPX3, HRSP12, MSRA, MSRB1, and CRYAB, protect the cell and/or cellular proteins during stress." (PMID 37216114, 2023).
neurodegenerative disease (1 paper, 2020). A disorder of the central nervous system characterized by gradual and progressive loss of neural tissue and neurologic function. "The overall implication of these MsrA-dependent phenomena is abolishing the expression of biomarkers that are associated with neurodegenerative diseases, such as AD and Parkinson’s disease (PD; through an enhanced ubiquitination of 14-3-3 ζ)." (PMID 32456285, 2020). "In addition, overexpression of MsrA in the brain, through novel treatments, is anticipated to protect against the expression of biomarkers associated with neurodegenerative diseases." (PMID 32456285, 2020). "Establishing the role of MsrA as a positive regulator of Jab1 will have implications for the general function of MsrA in mediating protein ubiquitination/neddylation, as well as to enhancing cell survival, especially in neurodegenerative diseases." (PMID 32456285, 2020).
MSRA also shares sentences with these, for which no sentence is quoted: autism (2 papers); bipolar disorder (2); cardiovascular diseases (2); diabetes mellitus (2); endocarditis (2); Parkinson disease (2); Tinnitus (2); type II diabetes (2); age (1); alcohol use disorder (1); atrial fibrillation (1); Barrett's oesophagus (1); cardiac ischemia (1); cat-eye syndrome (1); dyslipidemia (1); emphysema (1); epilepsy (1); HIV-1 infection (1); hyperuricemia (1); hypophosphatasia (1); influenza (1); late-onset Alzheimers disease (1); leukemia (1); lip sarcoma (1); lung carcinoma (1); metastatic tumor (1); mood disorder (1); neurodevelopmental disorder (1); oesophageal adenocarcinoma (1); pancreatic ductal adenocarcinoma (1).
A further 8 diseases each share a sentence with MSRA in 1 paper.